CTLA4 (cytotoxic T-lymphocyte associated protein 4)
Diseases named in the same sentence as CTLA4 in open-access papers (continued):
Sharing a sentence is not in itself a finding about the gene and the disease.
melanoma (continued). "The anti-CTLA-4 monoclonal antibody (mAb) ipilimumab was the first ICI approved by the US Food and Drug Administration (FDA) in 2011 for the treatment of advanced melanoma." (PMID 37239166, 2023). "Based on this understanding, a monoclonal antibody against CTLA-4 (ipilimumab) was approved by the Food and Drug Administration (FDA) for the treatment of melanoma." (PMID 37765273, 2023). "Dual immune checkpoint inhibitors (the combination of anti-PD-1 and anti-CTLA-4 therapy) is considered as a promising therapy to enhance ICI efficacy and showed improved prognosis in melanoma and NSCLC." (PMID 36895477, 2023). "We formulate a simple ODE model to investigate the treatment of murine model of malignant melanoma B16-CD2 using OVT and anti-CTLA-4." (PMID 36766849, 2023). "The first ICI against CTLA-4 was named Ipilimumab, and got FDA approval for melanoma treatment in 2011, while the first PD-L1 ICI against melanoma was Pembrolizumab and got FDA approval in 2014." (PMID 37445336, 2023). "Ipilimumab, a CTLA4 inhibitor, was the first ICI approved by the U.S. Food and Drug Administration (FDA) in 2011 for the treatment of advanced-stage melanoma." (PMID 37232846, 2023). "Chronic exposure of B16 mouse melanoma cells to IFN-γ stimulates the expression of the checkpoint receptors PD-1, CTLA-4, LAG-3, and of TIM-3 ligands, as well as the resistance to combined ICB therapies in tumor grafts." (PMID 38304252, 2023). "The 02A sub-study (NCT04305041) randomizes patients with PD-1 refractory melanoma to receive vibostolimab (MK-7684) (anti-TIGIT), pembrolizumab and quavonlimab (anti-CTLA-4); pembrolizumab, quavonlimab and lenvatinib; or pembrolizumab and ATRA." (PMID 37345056, 2023). "To validate the ICR/GIE stratification, we assembled a cohort of 83 melanoma cases treated with ICI, either anti-CTLA4 or -PD-1, from previous published studies for which TMB, neoantigen load and gene expression were available." (PMID 37739939, 2023). "YUMMER1.7 is an immune competent melanoma model, relatively resistant to immunotherapy with anti-PD1 + anti-CTLA4 as the majority of YUMMER1.7-bearing mice have tumor progression on anti-PD1 monotherapy and do not reject their tumors." (PMID 37964379, 2023). "The authors also found that the combination of CIS inhibition with CTLA4 and PD1 blockade had a greater effect in reducing melanoma metastasis than either of these treatments alone." (PMID 37371615, 2023). "The greatest reduction of mortality is owing to the improvement of checkpoint therapies, and the clinical use of CTLA4 and PD1 inhibitors has benefited many melanoma patients, greatly improving disease-free survival and OS." (PMID 36674798, 2023). "These questions are clinically relevant as anti-PD-1 and anti-CTLA-4 antibodies, used alone or in combination, are the second-line treatment option for BRAFV600 patients with melanoma resistant to targeted therapies." (PMID 37175614, 2023). "A study showed that, under the background of anti-CTLA-4 immunotherapy, host-derived IDO can inhibit the infiltration and accumulation of tumor-reactive T cells in B16 melanoma tumors and weaken the anti-tumor efficacy." (PMID 35799264, 2022). "PDCD1 and CTLA-4 antibodies, which are immune checkpoint inhibitors, have been approved for the treatment of cancers including non-small cell lung cancer (NSCLC) and melanoma, and have improved the prognosis of patients with these cancers." (PMID 36385955, 2022). "The limited treatment of choice for advanced melanoma is immune checkpoint blockade (ICB) and molecularly targeted therapies, such as CTLA-4, PD-1/PD-L1 inhibitors, and BRAF inhibitors due to melanoma's high level of heterogeneity and aggressiveness." (PMID 36467505, 2022). "In another preclinical study, the small molecule TRT agent 177Lu-LLP2A, targeting very late antigen-4 (VLA-4), when combined with anti-CTLA-4, anti-PD-1, or anti-PD-L1 resulted in improved survival of mice bearing B16F10 melanoma tumors." (PMID 36678756, 2022).
melanoma (continued). "Historically, ORR is higher for combined CTLA-4 and PD-1 inhibitor therapy than for either single agent CTLA-4 (i.e., ipilimumab), or PD1-inhibitors (i.e., nivolumab or pembrolizumab) in a melanoma population." (PMID 36547123, 2022). "In contrast to IFNγR1KD melanomas, IFNγR1KO melanomas show a reduced abundance of CD8+ T cells at the baseline and lack increased infiltration and functional rejuvenation of TILs upon anti-CTLA-4 therapy." (PMID 36008408, 2022). "Immune checkpoint inhibitors that are currently approved by the US Food and Drug Administration for melanoma include anti-PD-1 (nivolumab and pembrolizumab), anti-PDL-1 (avelumab and atezolizumab), and anti-CTLA-4 inhibitors (ipilimumab)." (PMID 36160103, 2022). "The integration with single-cell transcriptome datasets from melanoma patients treated with ICB (anti-PD1, anti-CTLA4 and anti-CTLA4 plus anti-PD1) led to the refinement of a specific B lineage-related subtype associated with response: Plasma cells." (PMID 36012390, 2022). "In melanoma, prostate, and also PDA murine model, GMCSF cell-based vaccines combined with CTLA-4 inhibitor decreased tumour growth and restored the antitumor immunity." (PMID 35621637, 2022). "Conversely, the CM T-cell data obtained from a previously published melanoma single-cell dataset that we downloaded, the expression of PDCD1 and CTLA-4 was higher than that of TNFRSF9." (PMID 35894206, 2022). "Two clinical studies on melanoma patients, using T-VEC and either anti-PD-1 or anti-CTLA-4 antibody, have demonstrated striking efficacy for this combinatorial approach." (PMID 36221123, 2022). "In stage III melanoma patients, a phase III clinical trial with anti-CTLA4 therapy demonstrated that 54.1% of patients developed grade ≥3 irAE symptoms." (PMID 35741331, 2022). "The first targeted drug for CTLA-4, ipilimumab, was approved by the Food and Drug Administration (FDA) in 2011 to treat melanoma." (PMID 35836577, 2022). "Ipilimumab treatment, targeting CTLA4, after CRT has been approved by the FDA for irresectable melanoma." (PMID 35566403, 2022). "Growth of B16 melanoma was considerably delayed compared to wild-type mice, and overall survival rate was improved in IDO knockout mice treated with anti-CTLA-4." (PMID 35799264, 2022). "The few studies to date have only incorporated pembrolizumab, nivolumab (anti‐PD‐1) and ipilimumab (CTLA‐4) therapy, and other ICIs or combination therapies with SOC therapies have only been described for feasibility studies in melanoma." (PMID 35782339, 2022). "Here the authors report that melanoma cells with knockout of IFNγR1 show constitutive JAK1/2 activation and that the JAK1/2 inhibitor ruxolitinib can overcome resistance to anti-CTLA-4 therapy." (PMID 36008408, 2022). "On the other hand, therapy with the anti CTLA-4 monoclonal antibody tremelimumab was shown to restore CD4+ and CD8+ T-cells in 7 of 10 patients with pretreated advanced melanoma and severe lymphopenia." (PMID 35805052, 2022). "Immune checkpoint blockades (ICBs), including antibodies to PD‐1, PD-L1, and CTLA-4, have been licensed by FDA and have been clinically effective against most types of cancer, such as malignant melanoma." (PMID 36177041, 2022). "Asian patients with melanoma were found to have lower levels of certain ICI therapeutic targets (PD-L1, CTLA-4, and IDO-1) than Caucasian patients in an analysis of RNA sequencing expression profiles." (PMID 36289601, 2022). "Studies have shown that the anti-tumor action of CTLA-4 blockers depends on different bacteriophage types, and that CTLA-4 antibody treatment of melanoma patients favors the growth of Bifidobacterium fragilis, which has anti-cancer properties." (PMID 36177041, 2022). "CTLA4, an immunological checkpoint molecule, can influence the TME of CM by binding to B7 (CD80/CD86) molecules on melanoma antigen-presenting cells to down-regulate T cell activation." (PMID 35957907, 2022).
melanoma (continued). "Our initial results were entirely consistent with and extended such findings in that we were able to observe an astonishing anti-tumor resistance in hard-to-treat mouse models such as the anti-CTLA-4- and anti-PD-1-refractory YUMM1.7 mouse melanoma." (PMID 35969037, 2022). "ICIs specific for checkpoint proteins, such as CTLA-4 or PD-1, have been approved for the treatment of several cancer types, including non-small cell lung cancer (NSCLC), melanoma, head and neck cancer, bladder cancer, and renal cell cancer." (PMID 36679904, 2022). "Bicarbonate administration has been reported to control melanoma growth, increase CD8+ T cell infiltration and NK and B cell activation, and improve anti-CTLA4 and anti–PD-1 therapy and adoptive cell therapy in B16 melanoma–bearing mice." (PMID 36233246, 2022). "Another retrospective study was performed on patients with advanced melanoma and PAD who had received a combination of anti-CTLA-4 and anti-PD-1 therapy." (PMID 36678712, 2022). "For advanced melanoma, 5-year overall survival reached 26% for anti-CTLA4 monotherapy, 44% for anti-PD1 monotherapy and 52% for the combined (anti-CTLA4 plus anti-PD1) treatment, yet a large proportion of patients exhibit primary resistance." (PMID 36230753, 2022). "Serum samples of 45 unresected stage III and IV melanoma patients were analyzed before administration (baseline) and during ICI with anti-CTLA-4 and anti-PD-1 antibodies." (PMID 36428768, 2022). "This monoclonal antibody to human CTLA-4 was approved by the Food and Drug Administration (FDA) in 2011 to treat malignant melanoma; this was the first clinical use of an immune checkpoint inhibitor (CPI) in cancer treatment." (PMID 35628647, 2022). "In a mouse melanoma model, inhibition of both CD73 and A2aR increased CTLA-4 the therapeutic effect." (PMID 36159861, 2022). "A recent study using an anti-CTLA-4 expressing NDV OVT found the treatment was similar in effectiveness to traditional anti-CTLA-4 therapy in combination with radiation, in B16-F10 melanoma." (PMID 35515106, 2022). "CTLA-4 blockade therapy with the mAb ipilimumab and tremelimumab were developed, and ipilimumab has received FDA approval for treating advanced melanoma and other cancers in combination therapies." (PMID 35625811, 2022). "Profound responses have been seen in patients with melanoma and non-small cell lung carcinoma (NSCLC) using therapies targeting the programmed death (ligand)-1 (PD[L]-1) and cytotoxic T-lymphocyte antigen-4 (CTLA-4) signaling pathways." (PMID 35690784, 2022). "We found that in the melanoma cohort treated with both PD1 and CTLA4, the likelihood of predicting a positive immunotherapy response is strong with AUC=0.800." (PMID 36147906, 2022). "Here we show, by metabolic profiling of plasma samples from melanoma-bearing mice undergoing anti-PD1 and anti-CTLA4 combination therapy, that higher levels of purine metabolites, including inosine, mark ICB sensitivity." (PMID 36109526, 2022). "Immune checkpoint inhibitors (ICIS) such as ipilimumab (CTLA-4 inhibitor) and nivolumab (PDCD-1 inhibitor) significantly improve the overall survival rates of patients with melanoma and advanced liver cancer." (PMID 35769911, 2022). "Patients with advanced stage IIIc and stage IV NM and SSM treated with anti-CTLA-4 and/or anti-PD-1, or BRAF/MEKi in the first line, were included from the prospective Dutch Melanoma Treatment Registry." (PMID 36428787, 2022). "A total of 333 patients were diagnosed with melanoma, non-small cell lung carcinoma (NSCLC), or renal cell carcinoma (RCC) and treated with anti-PD-1, anti-PD-L1, or anti-CTLA-4 therapy." (PMID 35634306, 2022). "In melanoma and NSCLC, ICB targeting the immune checkpoint proteins PD-L1 and CTLA4 have resulted in improved patient survival due to reinvigoration of exhausted T cells." (PMID 34987640, 2022).
melanoma (continued). "The RAS inhibitor rigosertib has been shown to block AKT activation and synergize with anti-PD-1/anti-CTLA-4 in B16F10 (NRASWTBRAFWT) and YUMM3.3 (BRAF-mutant) melanoma preclinical models." (PMID 35806358, 2022). "In melanoma patients, TIGIT+ Tregs exhibited greater immunosuppressive capabilities and stability than TIGIT- Tregs by increasing the expression of CTLA-4, CD39, PD-1, and TIM3." (PMID 35345849, 2022). "Whole genome or exome sequencing (WGS/WES) data and clinical response information were available for 287 melanoma or NSCLC samples treated with the drug anti-PD1, anti-CTLA4, or their combination." (PMID 36139377, 2022). "Dual checkpoint blockade with PD-1 and cytotoxic T-lymphocyte antigen (CTLA)-4 inhibition is another approach that has been evaluated in NSCLC, RCC, and melanoma." (PMID 35414591, 2022). "This study assessed risk factors and the results of treatment with anti-PD-1 antibodies, anti-CTLA4 antibodies and BRAF/MEK inhibitors for advanced malignant melanoma." (PMID 35406444, 2022). "have discussed how NDV treatment reactivates the melanoma immune landscape through T and NK cells, MCH I and II, and interferon signaling to provide a synergistic effect when combined with anti-CTLA-4 therapy in B16-F10." (PMID 35515106, 2022). "All three categories of drugs, anti-PD1, anti-PD-L1, and anti-CTLA-4, have demonstrated efficacy against BMs from NSCLC and melanoma." (PMID 36612116, 2022). "Ipilimumab is a fully human IgG1 monoclonal antibody (mAb) targeting CTLA-4; it was the first FDA-approved ICI in 2011 for patients suffering from advanced melanoma." (PMID 35392976, 2022). "We and others have recently shed new light on the immunomodulatory effects of CDK4/6i, both alone and in combination with current melanoma standard-of-care therapies, including ICI (targeting PD-1, PD-L1, and CTLA-4) and targeted BRAF and MEK therapies." (PMID 35444175, 2022). "Ipilimumab, a CTLA-4 inhibitor that was approved by FDA in 2011, was the first ICI to treat advanced unresectable melanoma due to its clinical benefit." (PMID 36499102, 2022). "Targeting either PD-1/PD-L1 or CTLA-4, the ICIs can improve overall survival (OS) and progression-free survival (PFS) and increase the long-term survival rate in patients with advanced melanoma." (PMID 35990677, 2022). "TIDE predicts the outcome of melanoma and NSCLC patients treated with anti-PD1 or anti-CTLA4 by signatures of T cell dysfunction." (PMID 36139377, 2022). "Anti-PD-1 therapy can lengthen both PFS and OS in advanced melanoma patients as a first-line drug recommended by the NCCN guidelines, whose clinical performance is superior to anti-CTLA-4 therapy." (PMID 35990677, 2022). "Poly(I:C) ameliorated melanoma- inhibition of ICOS, ICOSL and CD28 while abrogating the ability of B16 cells to stimulate CTLA-4." (PMID 36618349, 2022). "Similar results were also found in the other tumor cohort (p = 0.0041, log-rank test) and two melanoma cohorts (GSE91061, anti-PD-1 cohort:p = 0.044; and PRJEB23709, anti-PD-1 and anti-CTLA4 mixed cohorts:p = 0.01; log-rank test)." (PMID 35592529, 2022). "Currently, anti-PD-1 and anti-CTLA4 antibodies and BRAF/MEK inhibitors are the mainstay of treatment of advanced, inoperable or disseminated malignant melanoma." (PMID 35406444, 2022). "Co-injection of cGAMP with PD-1 or CTLA-4 inhibitor exhibited an enhanced anti-tumor effect and increased tumor-infiltrating CD8+ T cell responses in a mouse model of melanoma and an ex vivo model of cultured human melanoma explants." (PMID 35889509, 2022). "This study describes a biomarker-driven workflow to generate a transplantable mouse melanoma model responsive to anti-PD1 and anti-CTLA4 immunotherapy." (PMID 36230753, 2022). "Ipilimumab, also known as an anti-CTLA-4 (cytotoxic T-cell lymphocyte-liked protein 4) antibody, was the first immune checkpoint inhibitor authorized by the FDA to treat melanoma in 2011." (PMID 36363529, 2022).
melanoma (continued). "In recent years, anti-CTLA4 and anti-PD1 have significantly improved the prognosis of late melanoma and increased the OS of patients in tumor immunotherapy (PMID: 34509219)." (PMID 36059641, 2022). "A further subgroup analysis was performed according to the following variables: cancer type (NSCLC and melanoma) and ICI type (anti-CTLA-4, anti-PD-1, and anti-PD-L1)." (PMID 35603146, 2022). "EZH2 was also shown to be upregulated in response to TNFα induced by CTLA-4 blockade and IL2 agonist treatment in B16 and RIM3 melanoma models." (PMID 33859645, 2021). "Further, in melanoma and HNSCC notable expansion of neoantigen-specific T cell populations has been observed following both a-CTLA4 and a-PD-1 administration, with the expansion of these populations temporally aligning with lesion regression." (PMID 34439399, 2021). "In melanoma patients, increased levels of VEGF in the serum before treatment with the anti-CTLA4 immune checkpoint blockade antibody ipilimumab is predictive of worsened overall survival." (PMID 34680355, 2021). "This framework has been validated for melanoma, breast cancer, and NSCLC patients treated with anti-PD1, anti-PD-L1, anti-CTLA4 and epigenetic inhibitors." (PMID 34371708, 2021). "Latest studies on CTLA-4 and PD-1 blockade showed an upregulation of VISTA expression in prostate cancer and melanoma treated patients." (PMID 34728682, 2021). "Among them, MIR205HG expression is associated with the poor outcome of patient and its expression is positively correlated with the expressions of immune checkpoints like PD-1, CTLA4, LAG3, and TIM3 in adenocarcinoma and melanoma." (PMID 35096622, 2021). "Overall, the response ratios of melanoma to ICI therapy (combined with PD-1 and CTLA-4 inhibitors) were 66%, which was the highest among these ICI trails." (PMID 34220837, 2021). "CPEB3 is correlated with several critical pathways in melanoma, including PD1 signaling, CTLA4 pathway, CTCF pathway, CHEMOKIN signaling, VEGF signaling, and JAK-STAT pathway." (PMID 33506034, 2021). "All patients were treated with ipilimumab, a monoclonal antibody that blocks cytotoxic T-lymphocyte antigen 4 (CTLA-4) and received FDA approval for patients with previously treated advanced melanoma in 2011." (PMID 33902630, 2021). "Here, a cohort of melanoma patients who received anti-PD1 and anti-CTLA4 therapy (GSE91016) were also applied to evaluate the ICSscore application." (PMID 34646307, 2021). "In 2011, FDA approved the first anti-CTLA-4 monoclonal antibody, (called Ipilimumab (YERVOY®, IgG1)) for advanced melanoma." (PMID 35083014, 2021). "We developed a potential therapeutic strategy for the treatment of melanoma and NSCLC patients by cotreatment of Sunitinib and CTLA4 mAb." (PMID 33510997, 2021). "Compared with single-agent ICB therapy, combination treatment of anti-CTLA4 (ipilimumab) and anti-PDL1 (nivolumab or pembrolizumab) led to better tumor response and patient survival in melanoma, sarcoma, and small cell lung cancer." (PMID 33637086, 2021). "We then analyzed the difference between immune index and melanoma patients treated with anti-PD1 and anti-CTLA4 as well as urothelial carcinoma patients treated with PD-L1 under different responses." (PMID 35111149, 2021). "A monoclonal antibody to immune checkpoint CTLA-4 called ipilimumab, was the first ICI which gained approval to be used in the treatment of advanced melanoma." (PMID 34356899, 2021). "Ipilimumab, the first approved anti-CTLA-4 monoclonal antibody, slightly but significantly increased the OS of stage III/IV melanoma patients compared to standard treatments." (PMID 34336860, 2021). "In this study, 26 patients with advanced melanoma were treated locally by ILI with the nitrogen mustard-alkylating agent melphalan, followed by the systemic administration of CTLA-4 blocking the antibody (ipilimumab) in a phase II trial." (PMID 34771649, 2021).